ALDH1A3 (aldehyde dehydrogenase 1 family member A3)
Diseases named in the same sentence as ALDH1A3 in open-access papers (continued):
Sharing a sentence is not in itself a finding about the gene and the disease.
colorectal cancer (20 papers, 2018 to 2025). A primary or metastatic malignant neoplasm that affects the colon or rectum. "In colorectal cancer, ALDH1A3 upregulation is associated with acquired chemoresistance and metastatic dissemination." (PMID 33068330, 2020). "ALDH1 is abundant in tumor samples from patients with CRC, which can be used as a particular marker for CSCs of colorectal cancer, mainly including ALDH1A1, ALDH1B1, and ALDH1A3, are associated with poor prognosis and resistance to chemotherapy in colorectal cancer." (PMID 36387165, 2022). "The aryl hydrocarbon receptor is present in GBM and malignant gliomas, but it is still not known if t3IDA also plays a role in its activation in these tumors with an effect on ALDH1A3 transcription as described in colorectal cancer." (PMID 39001459, 2024). "In colorectal cancer, ALDH1A3 expression is targeted by long non-coding RNA (lncRNA) MIR600HG by binding to a sequence in its 3′UTR, resulting in reduced metastasis and chemosensitivity." (PMID 36672441, 2023). "In colorectal cancer cells, ALDH1A3 expression is induced via the Hippo pathway activator Yap by its RAR-RXR transcriptional coactivator activity." (PMID 36672441, 2023). "In colorectal cancer, ALDH1A3 was similarly found to induce LINC00284 (NRAD1); however, its cancer-promoting effects were mediated through miRNA interactions." (PMID 36672441, 2023). "Motivated by the role of CSCs in chemoresistance, we quantified the expression of several prominent CSC gene markers in colorectal cancer, i.e., ALDH1A3, CD166, CD133, and LGR5, following each cycle of treatment." (PMID 37791907, 2023). "Mechanistically, upregulation of ALDH1A3–Linc00284 promotes colorectal cancer invasion and migration by regulating miR-361-5p/TGFβ signaling pathway." (PMID 36275636, 2022). "Pieces of the literature suggested that MIR600HG suppressed metastasis and development by targeting oncogenic ALDH1A3 in colorectal cancer." (PMID 36186449, 2022). "ALDH1A3 and Linc00284 involve in colorectal cancer (CRC) development; however, the regulatory mechanism is still unclear." (PMID 36275636, 2022). "ALDH1A3 expression was higher in colorectal cancer tissues than that in adjacent tissues in Shanghai Ninth People’s Hospital cohort 1 (Jiuyuan cohort 1)." (PMID 33419984, 2021). "To further validate the pathologic significance of ALDH1A3 in colorectal cancer, we detected and compared ALDH1A3 expression by immunohistochemical (IHC) staining assay in 31 paired paraffin-embedded colorectal cancer and adjacent tissues." (PMID 33419984, 2021). "Upregulation of the ALDH1A3 isoform was correlated with acquired chemoresistance in colorectal cancer and cholangiocarcinoma." (PMID 31443351, 2019). "Our study demonstrated that the chemoresistant population, which can be selected during chemotherapy, leads to metastasition and overexpression of ALDH1A3 isoform in HT-29 colorectal cancer model." (PMID 30143021, 2018). "Its inhibition by siRNA approach partially sensitized cells to various agents, thus linking for the first time the ALDH1A3 and chemoresistance in colorectal cancer." (PMID 30143021, 2018). "In colorectal cancer, the ALDH1A3 promoter is overactivated by trans-3-indole acrylic acid (t3IDA)." (PMID 39001459, 2024). "However, the disulfiram copper complex CuET inhibited colorectal cancer progression by downregulating ALDH1A3 gene expression." (PMID 36672441, 2023). "Mechanistically, upregulation of ALDH1A3–Linc00284 promotes colorectal cancer invasion and migration by regulating the miR-361-5p/TGFβ signaling pathway, which might provide a new insight into the treatment of CRC." (PMID 36275636, 2022). "To validate the effects of JIB-04 on the mRNA expression of β-catenin target genes, we measured the mRNA levels of CSC-associated genes (CD44, LGR5, DKK1, ALDH1A3, ALDH1B1, CD24, and SOX4) by qRT-PCR in three different colorectal cancer cell lines after treament with JIB-04." (PMID 29700375, 2018).
colorectal cancer (continued). "Elevated expression of CSC markers CD166, ALDH1A3, CD133, and LGR5 was consistent with their role in drug resistance of colorectal carcinoma and correlation with a poor prognosis for patients." (PMID 37791907, 2023). "Our findings indicate that the ALDH1A3–Linc00284 axis mediates the progression of CRC by targeting TGFβ signaling via sponging miR-361-5p in CRC cells, providing new insight into the pathogenesis and treatment of colorectal cancer." (PMID 36275636, 2022). "According to colorectal cancer research, tryptophan metabolites derived from anaerobic bacteria, such as trans-3-indoleacrylic (IDA), act as endogenous ligands for the aryl hydrocarbon receptor (AHR), leading to the transcriptional upregulation of ALDH1A3 expression." (PMID 40708788, 2025). "As AMBRA1 affected CTNNB1 transcription via ALDH1B1, which is a crucial CSC marker of colorectal cancer, we next investigated whether AMBRA1 expression affects the mRNA levels of several CSC-related β-catenin target genes, including LGR5, HIF1a, ALDH1A3, CD24, and SOX4." (PMID 34769507, 2021).
pancreatic cancer (18 papers, 2013 to 2025). "It is noteworthy that analyses of the role of ALDH1A3 in glucose metabolism in pancreatic cancer showed differing results, where ALDH1A3 promotes pancreatic cancer progression and metastasis by increasing aerobic glycolysis." (PMID 39251846, 2024). "In pancreatic cancer cells, ALDH1A3 increases the expression of HK2 by its activation of the PI3K/AKT/mTOR pathway." (PMID 39251846, 2024). "It has been reported that ALDH1A3 activates the PI3K/AKT/mTOR signaling pathway by cross‐talking with the transcription factor PPARγ in pancreatic cancer." (PMID 37551838, 2023). "Knockdown of ALDH1A3 in HPAC pancreatic cancer cells reduced resulting lung metastasis when tail-vein-injected into mice." (PMID 36672441, 2023). "Analysis of downstream targets in pancreatic cancer cell lines identified that MEK/ERK/TSC/mTOR signaling is dependent on ALDH1A3 function and high expression of ALDH1A3 is associated with an aggressive subtype of PDAC." (PMID 27200288, 2016). "Validation in a second larger set of pancreatic cancer cell lines confirmed higher expression levels of ALDH1A3 as compared to the normal derived cell line and normal derived tissue samples." (PMID 24053169, 2013). "By selecting genes for further assessment based on this difference, we confirmed enhanced expression of aldehyde dehydrogenase 1A3 (ALDH1A3) in two larger sets of pancreatic cancer cell lines and in tumor tissues as compared to normal derived tissues." (PMID 24053169, 2013). "Moreover, gene expression analysis of the pancreatic cancer cell lines AsPC-1, BxPC3, and MiaPaCa-2 showed that AsPC-1 and BxPC3 cells mainly express ALDH1A3, while MiaPaCa-2 cells express ALDH1A1 and ALDH1A3 in equal levels." (PMID 37686694, 2023). "In addition, gene expression profiling of 3 pancreatic cancer cell lines indicated that AsPC-1 and BxPC3 cells primarily expressed ALDH1A3, whereas the expression of ALDH1A1 and ALDH1A3 in MIA PaCa cells was equivalent." (PMID 36651035, 2023). "ALDH1A3 promotes pancreatic cancer progression and metastasis by increasing cellular glycolysis." (PMID 36672441, 2023). "The presence of aldehyde dehydrogenase positive cells in tumor from patients with pancreatic cancer has been associated with decreased survival, and ALDH1A1 expression (ALDH1A3 was not tested) correlated with invasion of pancreatic cancer cell lines." (PMID 24053169, 2013). "As aldehyde dehydrogenase (ALDH) activity is a key feature of cancer stem cells, our results indicate that a member of the ALDH superfamily, ALDH1A3, may be upregulated in pancreatic cancer, where it could mark pancreatic cancer stem cells." (PMID 24053169, 2013). "ALDH1A3, another member of the ALDH superfamily, is found highly expressed in many different cancers, such as ovarian cancer and pancreatic cancer." (PMID 33068330, 2020). "It has been reported that knock-down of c-Met by siRNA and inhibitor treatment results in decrease of ALDH1A3 gene expression and ALDEFLUOR activity in pancreatic cancer cell lines with high levels of c-Met." (PMID 28966724, 2017). "In fact, pancreatic cancer tissues from our cases showed strong immunoreactivities for ALDH1A3 (data not shown)." (PMID 33427207, 2021). "Although we confirmed increased mRNA levels of ALDH1A3 in an independent set of pancreatic tissue samples and two series of cell lines, our finding should be validated in additional sample sets to thoroughly investigate the relationship between ADH1A3, cancer stem cells and pancreatic cancer." (PMID 24053169, 2013).
lung carcinoma (17 papers, 2015 to 2025). "In lung cancer cell lines, reduced ALDH1A3 expression was associated with decreased cell proliferation." (PMID 36672441, 2023). "We recently showed that USP22 may be associated with cisplatin resistance in lung cancer stem cell through downregulation of ALDH1A3." (PMID 31842906, 2019). "In this context, Hua and colleagues conducted a study to examine the regulatory connection between ALDH1A3 and PPARγ in the metabolism of lung cancer." (PMID 41304753, 2025). "The microarray dataset of 78 lung cancer cell lines revealed a substantial positive connection between PPARγ and ALDH1A3, a major enzyme involved in retinoic acid synthesis and NADH generation." (PMID 41304753, 2025). "Complementing tumor ALDH1a3, ALDH1a2 is found in the cancer stroma, such as the immunoregulatory mucosal myeloid regulatory DCs found in lung cancer patients or the M2 macrophages in glioblastoma that promote tumor tolerance." (PMID 39133222, 2024). "In a panel of lung cancer cell lines, ALDH1A3 knockdown reduced colony formation in 11 out of 12 cell lines." (PMID 36672441, 2023). "Activated STAT3 is more highly expressed in ALDH+ cells over ALDH- cells, and inhibition of STAT3 by small molecule inhibitor, Stattic, reduced ALDH1A3 expression in lung cancer stem cells." (PMID 31534498, 2019). "Promoter hypermethylation of ALDH1A3 has been reported to be a prognostic marker for lung cancer, gastric cancer, and invasive bladder cancer." (PMID 27484806, 2016). "Methylation of ALDH1A3 was originally reported in lung cancer and was identified as a methylation marker for other types of cancer, including breast, prostate, colon and brain tumors." (PMID 25789025, 2015). "Overall, ALDH1A3 has been identified as a novel metabolic target of PPARγ that has therapeutic implications, and this regulatory pathway is crucial in restricting the growth of lung cancer cells." (PMID 41304753, 2025). "ALDH1a1 has been implicated as an immunotherapy target in liver cancer through similar mechanisms as ALDH1a3 in sarcomas, suggesting that the immunotherapeutic-like effects of disulfiram in lung cancer may be due to ALDH1a1." (PMID 39133222, 2024). "We also revealed a significant association of high ALDH1A1 with never-smoker status, identifying ALDH1A1 and ALDH1A3 as possibly related to new risk factors in the ~10–20% of lung cancers occurring in never smokers." (PMID 32015486, 2020). "Notably, a recent study found that PPAR response elements (PPRE) existed in the promoter of ALDH1A3, and ALDH1A3 could up-regulate PPARγ in lung cancer cells, consistent with our observation in PDAC cells." (PMID 32612951, 2020). "Indeed, quantitative PCR analysis revealed that the mRNAs of two major ALDH isoforms expressed in the lung cancer cell lines, namely ALDH1A3 and ALDH1A1, were significantly reduced by the TKI treatment, which strongly discouraged their induction by cisplatin (p < 0.05)." (PMID 27486763, 2016). "Also for Non-small-cell lung carcinoma (NSCLC) ALDH1A3 was described as pre-dominant ALDH isoform, which on one hand associated with well differentiated lung cancer with good prognosis but on the other hand drives the tumorigenic and clonogenic potential of NSCLC cells." (PMID 26460734, 2015). "We conducted a meta-analysis based on The Cancer Genome Atlas and Gene Expression Omnibus data and detected genetic alterations in ALDH1A1, ALDH1A3, or ALDH3A1, 86% of which were gene amplification or mRNA upregulation, in 31% of nonsmall cell lung cancers (NSCLCs)." (PMID 32015486, 2020). "On the other hand, lung cancer exhibits a mixed feature of ALDH1A1 and ALDH1A3." (PMID 30220009, 2019). "Consistent with our findings, it has also been shown by others that overexpression of ALDH1A1 rather than other isoforms (ALDH1A3 and ALDH3A1) increased lung cancer cell transformation and CSC phenotype by activating stem cell drivers Nanog, Oct4, and Sox2." (PMID 28415606, 2017).
colon cancer (11 papers, 2015 to 2024). "The activity of ALDH1 is mainly due to the isoform ALDH1A3 and has been associated with metastatic disease in cancer as well acquired chemoresistance in colon cancer." (PMID 38124067, 2023). "At least in colon cancer, ALDH1A3 increases invasion by upregulating EMT-inducing transcription factor zinc finger E-box binding homeobox 1 (ZEB1) and SNAI2 and by inhibiting MET-promoting miR-200 family microRNAs." (PMID 39251846, 2024). "In colon cancer, ALDH1A3 upregulated transcription factor zinc finger E-box binding homeobox 1 (ZEB1) and snail family transcriptional repressor 2 (SNAI2) by inhibiting miR-200 family members, leading to increased invasion." (PMID 36672441, 2023). "In colon cancer cell lines, ALDH1A3 knockdown decreased cell proliferation and C-X-C chemokine receptor type 4 (CXCR4) expression, suggesting a potential connection between the two." (PMID 36672441, 2023). "We also evaluated the effect of the pentoxifylline-based treatments on the mRNA levels of three ALDH isoforms, among which the ALDH1A3 is known as the most abundant in colon cancer tissues." (PMID 37460938, 2023). "Most recently, ALDH1A3 was shown to affect colon cancer in vitro proliferation and invasion depending on CXCR4 status." (PMID 30087899, 2018). "A more recent report showed that miR-125a-5p plays an important role in inducing apoptosis through inhibiting the survival pathways mediated by aldehyde dehydrogenase 1a3 (aldh1a3) and myeloid leukemia–1 (mcl1) in colon cancer stem cells." (PMID 25504437, 2015). "ALDH1A3 was reported to affect colon cancer proliferation and invasion." (PMID 32377192, 2020). "An in vivo study on trans-retinoic acid and colon cancer found decreased ALDH1A1 and ALDH1A3 protein expression, while ALDH1A2 protein expression remained unchanged in colon cancer progression with alterations in the gut microbiome." (PMID 37711628, 2023). "In colon cancer, analysis of expression and knockdown of the 19 ALDH isoforms in 58 cell lines again suggested the primary importance of ALDH1A3 in the Aldefluor activity colon." (PMID 36672441, 2023).
ovarian cancer (11 papers, 2016 to 2025). A primary or metastatic malignant neoplasm involving the ovary. "ALDH1 is commonly used as a marker of ovarian cancer stem cells, and ALDH1A3 and FGF2 within the microenvironment preserve the stemness of cancer stem cells." (PMID 40507922, 2025). "Even though ALDH1A3 expression is elevated in primary ovarian cancer, high ALDH1A1 in tumors is correlated with a poor prognosis in patients, suggesting that ALDH1A1 is the more important target for improved survival." (PMID 35884498, 2022). "ALDH1A3, MARCKS, and COL5A1 were associated with reduced survival across all 3 datasets underscoring their relevance to ovarian cancer disease." (PMID 31534498, 2019). "Likewise in breast and ovarian cancers, the overexpression of ALDH1A3 correlates with poor prognosis and increased metastatic potential." (PMID 40887554, 2025). "The precise interactions among STAT3, ALDH1A3, and CD44 in ovarian cancer require further assessment." (PMID 31534498, 2019). "ALDH1A3 is also the primary ALDH1 isoform in human colon cell lines, and ALDH1A3 is highly expressed in ovarian cancer tissues." (PMID 30559934, 2018). "ALDH1A3, FGF2, and IL-6 have emerged as therapeutic targets for ovarian cancer." (PMID 40507922, 2025).
breast tumor (10 papers, 2011 to 2024). "We further confirmed the association of ABAT or GABRE expression with high ALDH1A3 in two independent datasets of primary breast tumors that later developed distal metastasis (GSE2034 and GSE12276)." (PMID 34989902, 2022). "Combined inhibition of ALDH1A3 and glycolysis best reduces breast tumor growth and tumor-initiating cells, suggesting that the combination of targeting ALDH1A3 and glycolysis has therapeutic potential for limiting CSCs and tumor progression." (PMID 39251846, 2024). "We assessed a cohort of 78 archived fixed primary, treatment naïve, human breast tumour samples for co‐expression between ALDH1A3 and tPA, uPA, and PAI‐2 (tumour pathology and clinical details summarized)." (PMID 37753740, 2024). "Citral can block ALDH1A3‐mediated breast tumor growth via blocking its colony formation ability and gene expression regulation activity, as well as regulating apoptosis and cell‐cycle markers expression." (PMID 36694633, 2023). "ALDH1A3 expression in the breast tumor cells results in decreased GABA and its intermediates N-acetylputrescine and glutamate, suggesting a potential increased utilization of GABA and/or its intermediates by cells expressing high levels of ALDH1A3." (PMID 34989902, 2022). "Integrated metabolomic and transcriptome data identified GABA metabolism as a primary dysregulated pathway in ALDH1A3 expressing breast tumors." (PMID 34989902, 2022). "Among the 19 ALDH isoforms expressed in humans, ALDH1A3 has been shown to correlate best with ALDH activity of patient breast tumor CSCs and cell lines." (PMID 26372732, 2015). "Together, this brain and lung metastasis data suggested that ABAT-low primary breast tumors (often with concurrent high ALDH1A3 expression) are highly metastatic and are agnostic to whether the metastatic site is enriched for GABA (i.e., the brain) or is depleted for GABA (i.e., the lung)." (PMID 34989902, 2022).